INS (insulin)
Diseases named in the same sentence as INS in open-access papers (continued):
Sharing a sentence is not in itself a finding about the gene and the disease.
diabetes (continued). "The glucose intolerance in correspondence with the impairment of insulin secretion was observed in male rats, which was the main cause of diabetes in LEA rats." (PMID 23691528, 2013). "The LEA rats develop late onset diabetes in correspondence with the impairment of the insulin secretion, which is caused by progressive fibrosis in pancreatic islets in age-dependent manner." (PMID 23691528, 2013). "In 1939, Himsworth postulated that type 2 diabetes mellitus was not only an insulin deficiency state but also a disease in which cells are unresponsive to insulin." (PMID 23573411, 2013). "ROS can function as signaling molecules to activate a number of stress sensitive pathways that are linked to insulin resistance, decreased insulin secretion, and content, ultimately leading to late complications of diabetes." (PMID 24324490, 2013). "Adjustment for Matsuda ISI alone largely abolished these associations demonstrating that low insulin sensitivity was the major mechanism explaining the worsening of hyperglycemia and the development of incident diabetes." (PMID 23840693, 2013). "Diabetes (Type II) generally occurs due to human genetically susceptibility, as aresult loss of insulin producing pancreatic β-cell cytotoxicity mediatedthrough the release of nitric oxide (NO)." (PMID 24349947, 2013). "Some risk factors that indicate insulin therapy for glycemic control in pregnancies complicated by diabetes have been studied before." (PMID 23976911, 2013). "“Furthermore, the (oral) medications can cause kidney damage” (5 years of insulin use/ 10 years of having diabetes)." (PMID 24164794, 2013). "Insulin dysfunction occurs in several pathologies, such as diabetes mellitus, which is associated with fertility problems." (PMID 24228182, 2013). "Type 2 diabetes mellitus is characterized by inadequate insulin secretion and insulin resistance (IR) and causes serious harm to humans, often leading to metabolic disorders involving carbohydrates, proteins and fats." (PMID 23652883, 2013). "The combination of insulin treatment and longer duration of diabetes has been associated with a particular high risk of death from cardiovascular disease." (PMID 23738538, 2013). "First, excess of glucocorticoids, as seen in Cushing syndrome, have been found to inhibit insulin secretion by pancreatic β cells and reduce insulin sensitivity in liver, skeletal muscle, and adipose tissue, as well as increase the risk of diabetes." (PMID 23229017, 2013). "Insulin resistance, a major abnormality underlying type 2 diabetes mellitus, is defined as the pathophysiological condition reducing insulin responsiveness in liver, muscle, and adipose tissue." (PMID 23590862, 2013). "Diabetes mellitus is a metabolic disorder of multiple etiologies, characterized by chronic hyperglycemia due to deficient secretion or action of insulin and, like obesity, is considered one of the main heath threats." (PMID 23983677, 2013). "And GK insufficiency, which is caused by insulin insufficient or insulin resistance in diabetes, can cause decreased utilization of glucose for energy production." (PMID 23762123, 2013). "The aim of our investigation was to study the consequence of TLR4 deficiency on the development of insulin-deficient diabetes in the NOD mouse." (PMID 24086519, 2013). "The metabolic pathways enriched only in male were associated with diabetes-related pathways, including insulin signaling, glycolysis and galactose metabolism." (PMID 24098417, 2013). "In previous analyses, we have shown that leptin is a major risk factor for diabetes in minimally adjusted models, yet appears as a protective factor after adjustment for adiposity, inflammation markers and insulin." (PMID 23806173, 2013). "Activation of inflammatory pathways in turn impairs insulin signaling, ultimately leading to obesity-associated type 2 diabetes mellitus." (PMID 23349837, 2013).
diabetes (continued). "The deficiency in islet β cell secretion and insulin sensitivity, the two important pathophysiological mechanisms of diabetes, are responsible for glycemic disorders." (PMID 23876034, 2013). "Diabetes is a disease caused by the loss or dysfunction of insulin-producing beta cells in the pancreas." (PMID 23382704, 2013). "The reduction in obesity-diabetes relative risk seen with adjustment for insulin is consistent with this view." (PMID 23806173, 2013). "The streptozotocin (STZ)-induced diabetes in a rat model is a T cell-mediated autoimmune disease associated with a marked decrease in insulin levels, exhibiting metabolic characteristics similar to those of type 1 diabetes in humans." (PMID 23573250, 2013). "An inverse association has been observed between BMI and insulin secretion among subjects with normal glucose tolerance and among patients with diabetes who have good glycemic control." (PMID 24370346, 2013). "Among people with diabetes, the highest risk of death from cardiovascular disease is found in those treated with oral hypoglycemic drugs or insulin and in those with longer duration of diabetes." (PMID 23738538, 2013). "Alpha-hydroxybutyrate (α-HB) has been found to be the most significant biomarker associated with insulin sensitivity, diabetes mellitus, and CVD." (PMID 24282409, 2013). "Nevertheless, results from human studies have been inconsistent, where disruptions in insulin signalling have been linked with age-related diseases such as insulin resistance and diabetes." (PMID 24381713, 2013). "Insulin resistance refers to the diminished effectiveness of insulin in lowering blood glucose levels, which is the main initial and independent risk factor for type 2 diabetes mellitus." (PMID 24371833, 2013). "Duodenal-jejunal bypass surgery in rats normalized glucose disposal in streptozotocin-induced diabetes as well as in insulin deficient autoimmune type 1 diabetes." (PMID 23437106, 2013). "The molecular mechanisms underlying the insulin-independent stimulation of glucose uptake and glycogen synthesis in skeletal muscles are of great therapeutic interest for diabetes mellitus." (PMID 23620811, 2013). "Recent studies have found that eating fast by self-assessed questionnaire was associated with a higher risk of diabetes in middle-aged Japanese males, and an increased HbA1c level in diabetic patients treated with insulin." (PMID 23755114, 2013). "We report a rare case of permanent neonatal diabetes (PND) due to insulin (INS) gene mutation in a 51-month-old girl who presented with hyperglycemia in the neonatal period." (PMID 23350652, 2013). "The original study investigating the polymorphism in T2DM demonstrated that the alanine allele of this polymorphism was associated with lower BMI, improved insulin sensitivity and thus reduced diabetes risk by 75%." (PMID 23306188, 2013). "Blood HMW adiponectin levels more definitively reflect BMI, the effect of body weight loss, glucose tolerance, insulin sensitivity in the liver, metabolic syndrome, and type 2 diabetes mellitus than the levels of total adiponectin." (PMID 23641944, 2013). "We found female gender, insulin use and diabetes complications to be significantly associated with poor HRQoL." (PMID 24349036, 2013). "MiRNAs play regulatory roles in many biological processes associated with diabetes, including adipocyte differentiation, metabolic integration, insulin resistance and appetite regulation." (PMID 24279768, 2013). "Unawareness of low blood glucose is eventually caused by recurrent hypoglycemia induced by intensive insulin therapy in diabetes, particularly type 1 diabetes mellitus." (PMID 24194729, 2013). "Type 2 diabetes mellitus is a metabolic disorder which causes hyperglycemia due to defect in insulin secretion and insulin resistance." (PMID 23762147, 2013). "STZ, as a highly cytotoxic agent of pancreatic β-cells, induces diabetes by damaging the cells that causes the reduction in insulin release." (PMID 24090482, 2013).
diabetes (continued). "Liver glucokinase activity was also markedly suppressed in animal models of diabetes, including the insulin-deficient streptozotocin model and the insulin-resistant Zucker Diabetic Fatty rat." (PMID 24371433, 2013). "Relapse of diabetes remission was associated with longer diabetes duration at baseline, higher baseline body weight, higher baseline plasma glucose, smaller weight loss at 2 years and a smaller reduction of plasma insulin at 2 years." (PMID 23515973, 2013). "It has been reported that female rats are less sensitive to insulin than males of all age groups and also more susceptible to the rapid development of a severe form of diabetes." (PMID 24499599, 2013). "In one of their early studies, offspring of diabetic dams had permanent hypoplasia of the VMN, decreased insulin responsiveness to glucose, impaired glucose tolerance, and increased susceptibility to diabetes." (PMID 23476780, 2013). "A modified view that accommodates heterogeneity of junction strengths in the islet can explain why, for example, a loss of gap junction conductance in diabetes is necessary for an increase in plasma insulin levels following hyperglycemia." (PMID 23936417, 2013). "Diabetes mellitus is a syndrome characterized by the loss of glucose homeostasis as a result of defects in insulin secretion and functionality." (PMID 24204387, 2013). "In multivariate analyses, female gender (P = 0.001), insulin use (P = 0.030), diabetes complications (P = <0.001) were significantly associated with more unhealthy days." (PMID 24349036, 2013). "As a group, Asian Indians tend to be insulin resistant and at high risk for diabetes and premature coronary heart disease when compared to other ethnic groups and this is partly explained by high visceral fat content." (PMID 23596520, 2013). "In support of this thesis, evidence suggests that the mechanisms underlying the association between pre-diabetes/metabolic syndrome and cancer incidence involves the influence of elevated insulin and IGF-1." (PMID 23405181, 2013). "Diabetes mellitus, as a risk factor for endometrial cancer (EC), causes an increase in insulin and IGF-1 concentrations in the blood serum." (PMID 24308813, 2013). "In the present study we demonstrated that PCB-77, a coplanar PCB abundant in the environment, as well as PCB-126, a coplanar PCB that has been linked to diabetes, both resulted in dose-dependent rapid impairment of glucose and insulin tolerance in lean mice." (PMID 23099484, 2013). "This is the case in individuals who develop diabetes, a progressive loss of the insulin secretory capacity of β-cells can appear much before the clinical diagnosis." (PMID 23497124, 2013). "Inactivating mutations result in impaired insulin release and hyperglycemia and are associated with familial forms of diabetes." (PMID 24348462, 2013). "The body mass index (BMI) is a measure of overweight or obesity, most often used to evaluate the associations among obesity, BMD, diabetes, and insulin secretion." (PMID 24358252, 2013). "Diabetes is a metabolic disease resulting from defects in insulin secretion and/or insulin action and is often associated with increased risk of coronary heart disease." (PMID 23829275, 2013). "Impaired insulin signaling, glucose intolerance and diabetes have been associated with the development and worsening of motor symptoms in Parkinson's disease." (PMID 24376773, 2013). "It has long been observed that BCAAs and AAAs correlate with obesity and serum insulin, but only recently have these amino acids been found to be closely associated with insulin resistance and pathogenesis of diabetes." (PMID 24339906, 2013). "Insulin dependent diabetes mellitus (IDDM)is caused by the progressive destruction of the insulin secreting pancreaticβ-cells." (PMID 24349947, 2013). "Disturbances of sleep leading to disruption of melatonin synthesis have therefore been linked to pathologically altered insulin secretion and diabetes." (PMID 23535335, 2013).
diabetes (continued). "While diabetes mellitus begins as a result of an impairment in insulin signaling (deficiency/resistance), numerous other factors quickly become altered making the pathogenesis of diabetic complications multi-faceted." (PMID 24391596, 2013). "Increased leptin levels following insulin treatment in rodents and in diabetic patients suggest the insulin deficiency as the cause of altered leptin levels in diabetes." (PMID 23853613, 2013). "Diabetes mellitus (DM) is a chronic metabolic disease which is characterized by hyperglycemia, absolute or relative deficiencies in insulin secretion, and/or insulin action." (PMID 23841103, 2013). "Type 1 diabetes mellitus (T1D) is a chronic autoimmune disease caused by the specific destruction of pancreatic β cells, which produce insulin." (PMID 23533683, 2013). "Individuals with abnormal insulin sensitivity in theabsence of diabetes and hypertension are also at an increased risk of arterial stiffness." (PMID 23671853, 2013). "In the past 30 years, lysosomes have also been subjected to investigation on association with insulin secretion, and human diabetes, as well as in animal models of diabetes." (PMID 23776622, 2013). "Here, the effect of quercetin on diabetes-induced exaggerated vasoconstriction in insulin deficient and insulin resistant rat models was investigated." (PMID 23717483, 2013). "The decrease of body fat stores in uncontrolled insulin-deficient diabetes results in marked reduce of plasma leptin levels." (PMID 23579596, 2013). "All forms of diabetes are characterized by a decrease in the circulating concentration of insulin (insulin deficiency) and a decrease in the response of peripheral tissues to insulin (insulin resistance)." (PMID 24416041, 2013). "To conclude, we report that the SPARC gene is expressed at detectable levels in human primary islets, and is associated with diabetes status and glucose stimulated insulin secretion in this tissue." (PMID 23840838, 2013). "Type 2 diabetes mellitus is a heterogeneous disorder associated with impaired insulin secretion from pancreatic β-cells and decreased insulin sensitivity which leads to hyperglycemia." (PMID 24319481, 2013). "Obesity in patients with T2DM is common and is frequently a major component of the metabolic syndrome, an insulin-resistant state that is characterized by a group of risk factors, which together confer an increased risk for cardiovascular disease and diabetes." (PMID 24499517, 2013). "This study provides an important pharmacological and therapeutic basis for the treatment of kidney diseases in the insulin-deficient diabetes." (PMID 23476687, 2013). "Diabetes mellitus type 1 is a multifactorial autoimmune disease characterized by complete destruction of pancreatic beta cells and loss of insulin production, caused by multiple genetic and environmental influences." (PMID 23935617, 2013). "We also found increased levels of TRAIL-R3, which has been linked to inflammation by regulation of apoptotic processes in immune cells and also to the loss of insulin-producing pancreatic beta cells in type 1 diabetes mellitus." (PMID 23915542, 2013). "Especially in developed and developing countries, type 2 diabetes mellitus is now considered a worldwide epidemic, and is characterized by defects in both insulin secretion and insulin action that causes a chronic hyperglycaemic state." (PMID 24090482, 2013). "Diabetes arises from irreversible destruction of pancreatic beta cells, causing degranulation and reduction of insulin secretion." (PMID 24719624, 2013). "Several longitudinal studies have demonstrated that individuals who are insulin resistant develop abnormal CVD risk factors long before the development of overt diabetes." (PMID 24163770, 2013). "Insulin-dependent diabetes mellitus (IDDM) is a disease caused by progressive destruction of the insulin secreting β-cells." (PMID 24416041, 2013).
diabetes (continued). "Diabetes as a risk factor in EC increases insulin and IGF-1 blood levels, both considered mitogenic factors contributing to the development of many cancers via enhanced cell proliferation." (PMID 24308813, 2013). "Over expressing in PTPN1 (encoding Protein tyrosine phosphatase 1B, PTP1B), a protein tyrosine phosphatase (PTP) that plays an overall positive role in insulin signaling, is linked to the pathogenesis of diabetes and obesity." (PMID 23774838, 2013). "In this regard, men with low insulin levels due to diabetes seem to have a decreased risk of PCa development." (PMID 24058525, 2013). "Risk of diabetes was assessed by serum glucose and insulin concentrations determined in a fasted state, and after an oral glucose tolerance test (OGTT)." (PMID 22828963, 2013). "While the use of exogenous insulin and other medications can control and sometimes prevent various diabetes-associated sequelae, numerous diabetic complications are still commonly encountered in diabetic patients." (PMID 24213655, 2013). "In contrast to females, males are specifically associated with diabetes-related pathways, including insulin signaling, glycolysis and galactose metabolism." (PMID 24098417, 2013). "STZ selectively destroys the pancreatic cells that secrete insulin, which causes less active pancreatic cells and produces diabetes mellitus." (PMID 24416041, 2013). "Accordingly, it is recognized that the impairment of insulin action in liver is a hallmark feature of type 2 diabetes mellitus." (PMID 23442260, 2013). "The higher production of insulin exposes obese women to an increased risk of developing diabetes mellitus, hence demonstrating the importance of preventing overweight or obese women from gaining too much weight during pregnancy." (PMID 23667649, 2013). "Most evidence linking hypoglycaemia to increased accident risk is based on insulin-treated diabetes." (PMID 23121373, 2013). "P58IPK knockout mice display increased islet apoptosis and become insulin deficient, mimicking diabetes-related β-cell failure." (PMID 23860123, 2013). "Insulin, insulin-like growth factor-1, and neurotrophin intranasal delivery has been suggested as a way to compensate for the neural damage caused by diabetes, stroke, diabetes, Alzheimer's disease, and HIV." (PMID 23431469, 2013). "Insulin dysfunction has been associated to a widely known metabolic disorder, diabetes mellitus (DM)." (PMID 24228182, 2013). "Diabetic retinal disease was significantly associated with diabetes duration (OR 1.12; 95% CI: 1.04–1.21) and insulin treatment (OR 8.21; 95% CI: 3.08–21.83)." (PMID 24260240, 2013). "Other explanations proposed have included the progressive development of beta cell exhaustion with insulin depletion and the association of diabetes with lower testosterone and insulin growth factor 1 (IGF1) levels." (PMID 24058525, 2013). "When subclinical cases of diabetes were excluded from the outcome, lactate was significantly associated with incident diabetes independently of insulin." (PMID 23383072, 2013). "For example, in mice genetically predisposed to develop diabetes (db/db), exendin-4 increased β-cell proliferation and islet mass, ameliorated the normal development of hyperglycemia, improved insulin secretion, and reduced HbA1c." (PMID 23256660, 2013). "Taken together, our results demonstrate that the progression of insulin-deficient diabetes in NOD mice is under control of TLR4." (PMID 24086519, 2013). "Insulin resistance or Type 2 Diabetes mellitus (T2DM) are often associated with impaired insulin signaling." (PMID 23544159, 2013). "We conclude that TLR4 is involved in the progression of the insulitis process thereby controlling the development of insulin-deficient diabetes in NOD mice." (PMID 24086519, 2013).